PDGFRA (platelet derived growth factor receptor alpha)
Diseases named in the same sentence as PDGFRA in open-access papers (continued):
Sharing a sentence is not in itself a finding about the gene and the disease.
osteoarthritis (2 papers, 2023 to 2026). A noninflammatory degenerative joint disease occurring chiefly in older persons, characterized by degeneration of the articular cartilage, hypertrophy of bone at the margins and changes in the synovial membrane. "Osteophyte, a common pathological outgrowth of cartilage and bone in osteoarthritis, originate from MPs expressing Pdgfrα in the periosteum and synovium." (PMID 37301964, 2023). "PDGFRα+GDF5.− MPs are activated at the periosteal-synovial junction near the articular cartilage with osteoarthritis." (PMID 37301964, 2023).
pituitary adenomas (2 papers, 2018 to 2020). "Although DNA methylation-induced PDGFRα and FGFR2 silencing has been reported in CG4 cells or primary human pituitary adenomas, the role of DNA methylation in regulating the expression level of these co-different genes and their effects on myogenesis or adipogenesis still remains unclear." (PMID 33308295, 2020).
rhabdoid tumor (2 papers, 2016 to 2024). An aggressive malignant embryonal neoplasm usually occurring during childhood. "To verify the clinical relevance of our findings, we evaluated the mRNA levels of PDGFRA and FGFR1 in an RNA sequencing (RNA-seq) dataset of 23 primary rhabdoid tumor (RT) patient specimens composed of 12 MRTs and 11 AT/RTs." (PMID 27783942, 2016). "We show that PDGFRα levels are regulated by SMARCB1 expression, and assessment of clinical specimens documents the expression of both PDGFRα and FGFR1 in rhabdoid tumor patients." (PMID 27783942, 2016).
serous ovarian carcinomas (2 papers, 2004 to 2014). "However, in our study, both KIT and PDGFRA expression were associated with aggressive tumour characteristics, such as high tumour grade, high proliferation index and poor patient outcome, suggesting them a role in the pathophysiology of at least a subset of serous ovarian carcinomas." (PMID 15583695, 2004). "We analysed the expression of KIT and PDGFRA by immunohistochemistry in 522 serous ovarian carcinomas, and mutations of KIT and PDGFRA by denaturing high-performance liquid chromatographyin 125 and 187 serous ovarian carcinomas, respectively." (PMID 15583695, 2004). "Using this as a reference, 12% of serous ovarian carcinomas showed decreased and 13% increased PDGFRA expression." (PMID 15583695, 2004). "Protein expression status of KIT and PDGFRA was performed by immunohistochemistry of tissue microarray containing 522 serous ovarian carcinomas." (PMID 15583695, 2004). "In conclusion, no mutations of KIT or PDGFRA were found, but a subset of serous ovarian carcinoma showed overexpression of the proteins, which was associated with aggressive tumour characteristics." (PMID 15583695, 2004). "PDGFRA immunostaining was interpretable in 505 (97%) of the 522 serous ovarian carcinomas." (PMID 15583695, 2004). "The lack of KIT and PDGFRA mutations seems discouraging as regards potential usefulness of imatinib mesylate in serous ovarian carcinoma." (PMID 15583695, 2004). "Prominent among these genes were those encoding platelet derived growth factor receptor alpha (PDGFRα), vascular cell adhesion molecule (VCAM), clusterin, intercellular adhesion molecule 1 (ICAM-1), and serine/threonine phosphatase 1 (Wip1), which are overexpressed in human serous ovarian cancer." (PMID 24603706, 2014). "No KIT or PDGFRA mutations were found in serous ovarian carcinomas." (PMID 15583695, 2004).
skin tumor (2 papers, 2013 to 2022). "Our attempts to establish CAF lines from Itga11-/- skin tumors using either the explant method or anti-PDGFRα antibody-based FACS were not successful, and thus, the functions and molecular mechanisms involving α11, PDGFRβ and TNC could not be studied further under in vitro conditions." (PMID 36003785, 2022).
small intestinal tumors (2 papers, 2016 to 2025). "Incorporating molecular correlates such as KIT, PDGFRA, and MMR status in future cohorts will not only clarify the genetic landscape of small intestinal tumors but also strengthen the translational link between immunohistochemical features and targeted therapeutic strategies." (PMID 41465833, 2025). "The clinical, pathologic and genetic features of NF1-GISTs differ from those of sporadic GISTs, including the development of multiple small intestinal tumors, an absence of KIT and PDGFRA mutations, and an indolent nature." (PMID 26511941, 2016).
soft tissue tumors (2 papers, 2014 to 2023). "Recognizing the frequent presence of Kit gene or PDGFRA gene mutations in GIST will facilitate the accurate classification of retroperitoneal soft tissue tumors." (PMID 36895492, 2023). "DOG1 is strongly expressed on the cell surface of GIST and is rarely expressed in other soft tissue tumors; it is also expressed ubiquitously in GIST irrespective of the c-kit or PDGFRA mutation status." (PMID 24932260, 2014).
subependymoma (2 papers, 2010 to 2023). Subependymoma is a rare and slow growing type of ependymoma, often presenting in middle-aged adults, found more commonly in men than in women, usually located in the fourth and lateral ventricles and manifesting with variable symptoms including headache, nausea, and loss of balance. "Immunoreactivity for HOXB13, NEFL and PDGFRα was strongest in MEPN and virtually absent in subependymoma." (PMID 19793339, 2010).
teratoma (2 papers, 2017 to 2023). A non-seminomatous germ cell tumor characterized by the presence of various tissues which correspond to the different germinal layers (endoderm, mesoderm, and ectoderm). "Within 4 months, Ki67+ teratomas were observed in all mice transplanted with PDGFRA− cells." (PMID 28410244, 2017). "In contrast, mice transplanted with PDGFRA+ cells did not form teratomas, even as far out as 8 months post-implantation." (PMID 28410244, 2017).
thymoma (2 papers, 2015 to 2017). A neoplasm arising from the epithelial cells of the thymus. "PDGFRA was expressed by medullary epithelial cells of fetal and postnatal normal thymus and by epithelial tumor cells in 10 analyzed thymomas." (PMID 27844328, 2017).
tuberous sclerosis complex (2 papers, 2017 to 2021). "We have previously demonstrated that hyperactivated mTORC1 signaling suppresses the expression of PDGFRα, safeguarding against the development of malignant tumors in tuberous sclerosis complex (TSC), a benign tumor syndrome affecting multiple organs." (PMID 33568640, 2021).
acute kidney injury (1 paper, 2023). Sudden and sustained deterioration of the kidney function characterized by decreased glomerular filtration rate, increased serum creatinine or oliguria. "Recent studies indicate that following acute kidney injury, PDGFRα-/PDGFRß+ (pericytes) and PDGFRα+/PDGFRß+ (kidney fibroblasts) cells migrate and proliferate and ultimately differentiate into myofibroblasts, which are the major source of increased extracellular matrix expression." (PMID 37963889, 2023).
acute pancreatitis (1 paper, 2020). An acute inflammatory process that leads to necrosis of the pancreatic parenchyma. "Studies have reported that ANGPT1 gene-modified human MSCs could promote angiogenesis and reduce acute pancreatitis in rats, while PDGFRA+ MSCs have enhanced skin repair/regeneration potential." (PMID 32252818, 2020).
adenosquamous carcinoma (1 paper, 2009). A carcinoma composed of malignant glandular cells and malignant squamous cells. "Assessment of EGFR, PDGFRA and VEGFR2 overexpression and activating gene mutations was performed in a cohort of 30 adenosquamous carcinomas of the uterine cervix." (PMID 19563658, 2009). "In conclusion, the present study is most the comprehensive analysis of EGFR, PDGFRA and VEGFR2 oncogenes in adenosquamous carcinoma." (PMID 19563658, 2009). "Despite the absence of EGFR and PDGFRA activating mutations, the presence of overexpression of these three important therapeutic targets in a subset of cases may be important in predicting the sensitivity of adenosquamous carcinoma to specific anti-RTKs drugs." (PMID 19563658, 2009).
allergic asthma (1 paper, 2025). A asthma with a basis in a pathological type I hypersensitivity reaction. "In this study, we dissected lung fibroblasts’ specific actions in allergic asthma development by establishing and studying mice with the loss of PDGFRα+ fibroblasts, known as resident lung fibroblasts." (PMID 41146597, 2025).
alopecia (1 paper, 2025). Hair loss usually from the scalp. "The mechanism behind ripretinib-related alopecia remains unclear but may involve the inhibition of kinases such as KIT, PDGFRA, VEGFR2, and BRAF, all of which have been linked to hair loss." (PMID 40231257, 2025).
aneurysm (1 paper, 2025). Bulging or ballooning in an area of an artery secondary to arterial wall weakening. "Collectively, although both PDGFRs in CD34+ cells play important roles in CD34+ cell proliferation and AAA progression, PDGFRb, rather than PDGFRa, is required for CD34+ cell transdifferentiation into Periostin+ myofibroblasts, thereby protecting aneurysms from rupture." (PMID 39731355, 2025).
ankylosis (1 paper, 2018). Fixation and immobility of a joint. "At the P42 endpoint of the natural history study, all surviving Pdgfrα-R206H mice were heavily burdened with HO and exhibited ankylosis of multiple joints." (PMID 30226468, 2018). "Joint ankylosis was common in P28 Pdgfrα-R206H mice, which weighed an average of 19% less than wild-type littermates (n = 11; p<0.01)." (PMID 30226468, 2018).
astrocytic tumor (1 paper, 2011). A glial tumor of the brain or spinal cord showing astrocytic differentiation. "Increased transcription of PDGFRα has been observed in astrocytic tumors, but gene amplification is detected only in a limited subset of GBMs (13%)." (PMID 24212955, 2011).
autism (1 paper, 2022). Persistent deficits in social interaction and communication and interaction as well as a markedly restricted repertoire of activity and interest as well as repetitive patterns of behavior. "We then analyzed the association of JUN and PDGFRA with human ASD risk genes from the Simons Foundation Autism Research Initiative (SFARI) database by NetworkAnalyst." (PMID 35655651, 2022). "We further explored the expression of JUN and PDGFRA in two relevant animal models of autism, the MIA and BTBR T+tf/J mouse models, which have been demonstrated to have increased Th17 cells and IL-17." (PMID 35655651, 2022). "JUN (DC = 19; BC = 3965), PDGFRA (DC = 40; BC = 3588), NTNG1 (DC = 47; BC = 4035) and GABRB1 (DC = 7; BC = 575) were associated with multiple neurodevelopmental disorders, including schizophrenia, bipolar disorder, Rett syndrome, seizures, and autistic disorder." (PMID 35655651, 2022).
autoimmune disease (1 paper, 2021). A disorder resulting from loss of function or tissue destruction of an organ or multiple organs, arising from humoral or cellular immune responses of the individual to their own tissue constituents. "Moreover, PDGFRA was identified and validated as a direct target of microRNA-146b in hematopoietic cells; recent work indicated that microRNA-146 family has a close relationship with inflammation and autoimmune diseases." (PMID 34573331, 2021).
benign gastrointestinal neoplasms (1 paper, 2025). "Other neoplastic lesions requiring differentiation include inflammatory fibroid polyp, benign gastrointestinal neoplasms associated with PDGFRA mutations and identified by CD34(+) and CD117(−) IHC profiles." (PMID 41262926, 2025).
bone metastasis (1 paper, 2015). Transfer of a neoplasm from its primary site to bones. "Stromal podoplanin, S100A4, and PDGFRα expression was elevated in bone metastasis, while tumoral podoplanin and stromal PDGFRβ expression was elevated in lung metastasis." (PMID 26163388, 2015).
brainstem tumors (1 paper, 2024). "Previous studies also demonstrated that PDGFRA amplification occurred more frequently in brainstem tumors, while fibroblast growth factor receptor 1 (FGFR1) mutation was usually limited in the thalamus." (PMID 38644565, 2024). "Previous studies indicated that PDGFRα amplification was frequently observed in DIPG or brainstem tumor." (PMID 38644565, 2024).
Cachexia (1 paper, 2020). Severe weight loss, wasting of muscle, loss of appetite, and general debility related to a chronic disease. "Four were common for local/cachexia (C1R, PRKCG, ELANE, SOST: all oppositely regulated) and four for metastatic/cachexia (SERPINA6, PDGFRA, PRSS2, PRSS1: all consistently changed), suggesting that stage and cachexia status might be molecularly separable." (PMID 33334063, 2020).
carotid body paraganglioma (1 paper, 2021). A benign or malignant extra-adrenal parasympathetic paraganglioma arising from paraganglia adjacent to or in the bifurcation of the common carotid artery. "It has been shown that carotid body paragangliomas in people, which are biologically similar to chemodectomas in dogs often overexpress VEGFR1, VEGFR2, PDGFRα, and PDGFRβ, making them potential targets for treatment with tyrosine kinase receptor inhibitors such as sunitinib." (PMID 33614771, 2021).
cerebrovascular diseases (1 paper, 2024). "As a specific receptor of PDGFA, PDGFRα is involved in a variety of pathways related to cardiovascular and cerebrovascular diseases and is of great significance for angiogenesis, inflammatory response, cell survival and apoptosis, cell proliferation and migration." (PMID 38195688, 2024). "Genes related to cardiovascular and cerebrovascular diseases annotated by the PI3K-Akt signaling pathway included Fgf12, Fgfr1, PDGFA, and PDGFRα." (PMID 38195688, 2024). "There were 6 genes related to cardiovascular and cerebrovascular diseases, which were Fgd3, Myoz3, AC095693.1, Adamts3, PDGFA and PDGFRα." (PMID 38195688, 2024).
cholestasis (1 paper, 2025). Impairment of the bile flow caused by obstruction within the liver, or outside the liver in the bile duct system. "In summary, we found that GCDCA can induce abnormal differentiation of HPCs into PDGFRA+CAFs in the cholestasis microenvironment, thus promoting the hepatocarcinogenesis." (PMID 41408647, 2025).
chorioamnionitis (1 paper, 2024). A morphologic finding indicating inflammation of the fetal sac membranes. "At the gene level, chorioamnionitis decreased the expression of PDGFC and PDGFRA and increased the expression of MBP, MAG, and MOG, consistent with our finding of decreased MBP at the protein level." (PMID 38200558, 2024).
chronic kidney disease (1 paper, 2020). Impairment of the renal function secondary to chronic kidney damage persisting for three or more months. "Hedgehog signaling regulates PDGFRA in vascular adventitial mesenchymal stem cells to promote neointima formation in arteriovenous fistula in chronic kidney disease." (PMID 33001865, 2020).
chronic neutrophilic leukemia (1 paper, 2014). A rare chronic myeloproliferative neoplasm characterized by neutrophilic leukocytosis. "We recently described a case of chronic neutrophilic leukemia associated with FIP1L1- PDGFRA rearrangement." (PMID 24669761, 2014).
chronic pancreatitis (1 paper, 2025). A chronic inflammatory process causing damage and fibrosis of the pancreatic parenchyma. "Alongside ADM, NGFR+/PDGFRα+ stromal cells delineate a remodeled lobular niche characterized by injury and chronic pancreatitis-like features, possibly providing a distinct microenvironment modifying tumor cell behaviour." (PMID 41006303, 2025).
cleft lip (1 paper, 2025). Congenital defect in the upper lip where the maxillary prominence fails to merge with the merged medial nasal prominences. "In craniofacial anomalies, polygenic burden modifies the penetrance of high-impact variants (e.g., PDGFRA) and helps localize effector cell types for non-syndromic cleft lip/palate (nsCL/P), providing a clearer mechanistic bridge from common variant load to disrupted facial morphogenesis." (PMID 41303669, 2025).
coloboma (1 paper, 2022). An abnormality in which a part of a structure in one or both eyes is missing. "Novel pathogenic variants in ANK3, BMPR1B, PDGFRA, and CDH4 were identified in 8 unrelated coloboma families." (PMID 35034853, 2022).
colorectal adenoma (1 paper, 2018). An adenoma that arises from the colon or rectum. "Using genome-wide DNA methylation analysis, we identified novel aberrant methylation profiles of genes including HLX, CUX2, MKX, NRG3 and PDGFRA associated with the colorectal adenoma-carcinoma sequence progression." (PMID 29945573, 2018).
colorectal GISTs (1 paper, 2025). "Surprisingly, gastric GISTs comprised 11.0% of cases, there were no colorectal GISTs, and 5.1% of NF1-GISTs harbored a KIT or PDGFRA mutation." (PMID 40043354, 2025).
Cough (1 paper, 2020). A sudden, audible expulsion of air from the lungs through a partially closed glottis, preceded by inhalation. "Chronic cough as presenting manifestation of platelet-derived growth factor receptor alpha (PDGFRA) + chronic eosinophilic leukaemia is being increasingly recognized." (PMID 32293378, 2020).
cyst (1 paper, 2023). A sac-like closed membranous structure that may be empty or contain fluid or amorphous material. "In addition, we isolated duct‐like cell‐fibroblast clusters from 4‐week‐old KC mice using mechanical dissociation and Fluorescence‐Activated Cell Sorting (FACS) with anti‐EpCAM/PDGFRα antibodies for cyst formation analysis and 3D spheroid assay." (PMID 37964407, 2023).
cystadenofibroma (1 paper, 2023). A benign or borderline neoplasm that arises from the ovaries and the fallopian tubes. "Additionally, as cells from high-grade serous OvCa, cystadenofibroma occasionally present weak expression of CAFs markers (PDGFRα, FAP)." (PMID 37958844, 2023).
disc degeneration (1 paper, 2023). "We identified nine clusters of stromal cells with well-defined progenitor marker genes, including PDGFRA and PROCR that were significantly increased in IDD patients and were related to the severity of disc degeneration." (PMID 37638033, 2023).
dysferlinopathy (1 paper, 2022). "NOX4-expressing PDGFRα+ cells were also found in the muscles of mice that model limb-girdle MD 2B (LGMD2B) (dysferlinopathy) and LGMD2F (δ-sarcoglycan deficiency); therefore, these observations are not restricted to dystrophin-deficient muscle." (PMID 36278481, 2022).
dysgerminoma (1 paper, 2012). A malignant germ cell tumor characterized by the presence of a monotonous primitive germ cell population. "If mutations in c-KIT or PDGFRA play a significant role in the development of GB and the development of dysgerminoma in DSD patients is not clear so far because of the lack of multiple studies." (PMID 22937135, 2012). "This indicates that mutations in PDGFRA do not play a major role in the development of (ovarian) dysgerminomas or GB." (PMID 22937135, 2012). "Sequencing PDGFRA did not reveal mutations in any of the dysgerminoma DNA samples analyzed, only a variation in exon 12 was found in almost all cases (homozygous synonymous SNP, rs." (PMID 22937135, 2012).
fibromyxoma (1 paper, 2022). "As c-KIT and PDGFRA gene sequencing was not performed then, this specimen was thus diagnosed as gastric wall plexiform fibromyxoma based on its morphology." (PMID 35720122, 2022).
germinoma (1 paper, 2010). A malignant germ cell tumor arising in the central nervous system. "In the germinoma group, the expression levels of RUNX1T1 and THRB were inversely correlated with expression of miR-146a, and the levels of NRP1, SVIL and PDGFRA were inversely correlated with the expression of miR-142-5p." (PMID 20178649, 2010).
gynecologic cancers (1 paper, 2020). "In gynecologic cancers, common genes regulated by prognosis-alternative miRNAs such as BCL2, EGFR, PDGFRA, and VEGFA were also demonstrated to be combinational targets for anti-cancer drugs." (PMID 32523951, 2020).
Hand-foot syndrome (1 paper, 2018). "A higher severity of AEs (grade ≥ 2 hand-foot syndrome) was collected with rs1800812 in PDGFRα." (PMID 29581831, 2018).